MIR519B (microRNA 519b)
Synonyms: hsa-mir-519b; MIRN519B; mir-519b
Gene: MicroRNA gene on chromosome 19 (53,695,213 to 53,695,293, forward strand). Ensembl gene ENSG00000207825.
Gene Ontology:
Biological process: miRNA-mediated post-transcriptional gene silencing
Homologues: Orthologues: chimpanzee ptr-mir-519b (100% identical), macaque mml-mir-519a-2 (90% identical). Paralogues in human: MIR519C (94% identical), MIR519A2 (93% identical), MIR516A1 (90% identical), MIR518B (90% identical), MIR520C (90% identical), MIR520F (90% identical), MIR523 (90% identical), MIR516A2 (89% identical), MIR518F (89% identical), MIR520E (89% identical), MIR526A1 (89% identical), MIR516B1 (88% identical), and 12 more.